SOX10 (SRY-box transcription factor 10)
Description:
Transcription factor that plays a central role in developing and mature glia (By similarity). Specifically activates expression of myelin genes, during oligodendrocyte (OL) maturation, such as DUSP15 and MYRF, thereby playing a central role in oligodendrocyte maturation and CNS myelination (By similarity). Once induced, MYRF cooperates with SOX10 to implement the myelination program (By similarity). Transcriptional activator of MITF, acting synergistically with PAX3. Transcriptional activator of MBP, via binding to the gene promoter (By similarity).
Synonyms: DOM; WS4; WS2E; SOX-10; PCWH; WS4C
Tractability: Antibody: UniProt places it where antibodies can reach, with medium confidence. PROTAC: ubiquitination databases record sites on it.
Safety:
Unwanted effects reported when the protein is acted on. In parentheses: how it was acted on, where the effect was seen, and who reports it.
neurotoxicity (source: ClinPGx)
Gene: Protein-coding gene on chromosome 22 (37,970,686 to 37,987,422, reverse strand). Ensembl gene ENSG00000100146.
Subcellular location: Cytoplasm; Nucleus; Mitochondrion outer membrane
Subcellular location (Human Protein Atlas): Nucleoplasm
Pathways (Reactome):
Developmental Biology: EGR2 and SOX10-mediated initiation of Schwann cell myelination; Regulation of MITF-M-dependent genes involved in pigmentation; Transcriptional and post-translational regulation of MITF-M expression and activity
Cell-Cell communication: Regulation of CDH19 Expression and Function
Gene Ontology:
Molecular function: identical protein binding; protein binding; sequence-specific double-stranded DNA binding; DNA binding; DNA-binding transcription activator activity; DNA-binding transcription activator activity, RNA polymerase II-specific; DNA-binding transcription factor activity; DNA-binding transcription factor activity, RNA polymerase II-specific; RNA polymerase II cis-regulatory region sequence-specific DNA binding; transcription cis-regulatory region binding; chromatin binding; DNA-binding transcription factor binding; promoter-specific chromatin binding
Biological process: anatomical structure morphogenesis; central nervous system myelination; enteric nervous system development; morphogenesis of an epithelium; negative regulation of transcription by RNA polymerase II; neural crest cell migration; oligodendrocyte development; oligodendrocyte differentiation; peripheral nervous system development; positive regulation of DNA-templated transcription; regulation of transcription by RNA polymerase II; cellular response to progesterone stimulus; cellular response to xenobiotic stimulus; developmental process; negative regulation of apoptotic process; negative regulation of canonical Wnt signaling pathway; negative regulation of DNA-templated transcription; negative regulation of Schwann cell proliferation; positive regulation of gene expression; positive regulation of gliogenesis; positive regulation of myelination; positive regulation of transcription by RNA polymerase II; regulation of DNA-templated transcription; stem cell differentiation; transcription elongation by RNA polymerase II
Cellular component: cytoplasm; nucleoplasm; nucleus; chromatin; mitochondrial outer membrane
Genetic constraint (gnomAD): Loss-of-function variants: 3 observed, 31.32 expected, observed/expected ratio (o/e) 0.0958, 90% interval 0.043 to 0.25. The upper end of that interval is the gene's LOEUF score, 0.25, which puts it in group 1 of 6, group 1 being the genes least tolerant of losing a copy. Missense variants: 430 observed, 627.98 expected, observed/expected ratio (o/e) 0.68, 90% interval 0.63 to 0.74. Synonymous variants: 283 observed, 277.29 expected, observed/expected ratio (o/e) 1.02, 90% interval 0.93 to 1.13.
Gene-disease validity (ClinGen):
ClinGen rates the evidence that SOX10 causes each of these diseases.
Waardenburg syndrome type 4C (autosomal dominant): Definitive. A subtype of Waardenburg syndrome type 4 (Waardenburg-Shah syndrome) caused by mutations in SOX10.
Homologues: Orthologues: chimpanzee SOX10 (99% identical), macaque SOX10 (99% identical), dog SOX10 (99% identical), pig SOX10 (99% identical), mouse Sox10 (98% identical), rabbit SOX10 (98% identical), guinea pig SOX10 (98% identical), rat Sox10 (97% identical), tropical clawed frog sox10 (74% identical), zebrafish sox10 (65% identical), Drosophila melanogaster Sox14 (18% identical), Drosophila melanogaster Sox21a (16% identical), and 2 more. Paralogues in human: SOX9 (56% identical), SOX8 (47% identical), SOX30 (21% identical), SOX4 (20% identical), SOX11 (19% identical), SOX17 (18% identical), SOX18 (18% identical), SOX1 (18% identical), SOX12 (17% identical), SOX7 (17% identical), CFAP65 (17% identical), SOX2 (17% identical), and 8 more.
Diseases named in the same sentence as SOX10 in open-access papers:
SOX10 is named in the same sentence as 320 diseases in open-access papers, as found by Europe PMC text mining. Sharing a sentence is not in itself a finding about the gene and the disease. The quoted sentences say what the papers report.
melanoma (476 papers, 2006 to 2026). A malignant, usually aggressive tumor composed of atypical, neoplastic melanocytes. "Therapy was associated with early and dramatic decreases of melanoma cell density in 4 of 5 patients (SOX10)." (PMID 41514118, 2026). "Immunohistochemical staining repeatedly demonstrated positivity for S100 and SOX10, with variable expression of melanocytic markers, underscoring the diagnostic ambiguity between desmoplastic melanoma and NF." (PMID 41828008, 2026). "The transcription factor SOX10 and the cytokine IL-33, both previously implicated in melanoma progression, were consistently overexpressed." (PMID 40647405, 2025). "We examined the dependency on YAP1 and TAZ expression of canonical TEAD targets in SOX10-deficient melanoma by siRNA knockdown." (PMID 41193428, 2025). "Somatic mutations in SOX10 occur in early-stage melanoma, with SOX10 upregulating MITF, MET, and Nestin expression in melanoma and responding to Wnt signals." (PMID 41012776, 2025). "Pathological diagnosis involves identifying melanin granules and using melanoma markers such as S-100, SOX-10, and HMB-45 to improve diagnostic accuracy." (PMID 40589645, 2025). "One interesting observation of our melanoma studies is evidence that loss of melanoma genetic dependencies like SOX10 (as suggested by the human DepMap data) can still lead to a small number of tumors, albeit with seemingly different biological behaviors." (PMID 40879132, 2025). "We found that HK2 specifically regulates translation of the mRNA encoding SOX10, a transcription factor implicated in the regulation of tumor initiation, maintenance, and progression in melanoma." (PMID 40956859, 2025). "Another study showed that PMP2 expression in melanoma cells is regulated by the transcription factor SOX10 and is linked to melanoma cell invasivenes." (PMID 40538623, 2025). "We observed a greater enrichment in all 4 gene sets following TAZ knockdown compared to YAP1 knockdown, suggesting that TAZ is responsible in melanoma cells depleted of SOX10 for mediating the expression of genes associated with these YAP1/TAZ signatures." (PMID 41193428, 2025). "The authors analyzed the gene expression levels of ligands and receptors previously associated with the SOX10/MITF axis in melanoma cell lines." (PMID 40872623, 2025). "SOX10 deficiency sensitizes melanoma cells to pyroptosis induced by TNFα and IFNγ, triggering caspase-dependent mechanisms that enhance ICD." (PMID 41235238, 2025). "For example, astragalin demonstrates cytotoxic properties and apoptosis induction by modulating critical melanoma-associated proteins such as caspase-9/3 and SOX10." (PMID 40508400, 2025). "Loss of SOX10 induces an undifferentiated melanoma phenotype characterized by slow growth, increased metastatic potential, and MAPK inhibitor (MAPKi) resistance." (PMID 38994683, 2024). "SP‐01 highly mimicked MPNSTs histologically but expressed S100B, p75, and SOX10 neural crest markers, like melanomas, and presented a high mutation frequency, mostly associated with the skin cancer COSMIC mutational signature." (PMID 37798904, 2024). "Remarkably, we found that the EP300 and SOX10 gene loci on chromosome 22 are frequently co-amplified in melanomas, including UV-associated and acral tumors." (PMID 38994683, 2024). "In this study, we report that the lysine acetyltransferase (KAT) EP300 and SOX10 gene loci on chromosome 22 are frequently co-amplified in melanomas, including UV-associated and acral tumors." (PMID 38994683, 2024).
melanoma (continued). "SOX10 is a lineage-specific transcription factor critical for melanoma tumor growth; on the other hand, SOX10 loss-of-function drives the emergence of therapy-resistant, invasive melanoma phenotypes." (PMID 38994683, 2024). "It is useful for identifying metastatic melanoma in sentinel lymph nodes and higher expression of SOX10 has been associated with melanoma progression and aggressiveness." (PMID 39329865, 2024). "Our results are corroborated by findings suggesting an association between treatment-induced SOX10 expression and a slow-cycling phenotype in both glioma and melanoma." (PMID 39285246, 2024). "Overall, our data suggest that the pathway mediating oncolytic resistance is due to the loss of SOX10 during acquired drug resistance in melanoma." (PMID 38201278, 2023). "SOX10 as a neural crest marker can be considered an early differentiation melanocyte marker and in melanoma cells has been associated with melanoma cell proliferation, tumor formation, and growth." (PMID 37628992, 2023). "That study also identified a vulnerability in SOX10-deficient melanoma cells, specifically an up-regulation of cellular inhibitors of apoptosis-2 (cIAP2)." (PMID 38132479, 2023). "TLR5 can effectively alleviate the stimulation caused by radiation, and SOX10 independently regulates the expression of IRF1 in melanoma through the JAK-STAT signaling pathway." (PMID 37113996, 2023). "Chronic vemurafenib treatment led to the loss of SOX10 in melanoma cells and a marked reduction in VSVΔ51 infection." (PMID 38201278, 2023). "The loss of SOX10 led to the development of an invasive, slow-cycling state in melanoma cells, promoting tolerance to BRAF and/or MEK inhibitors, which are commonly used in melanoma treatment." (PMID 38132479, 2023). "In a panel of melanoma cell lines, we monitored gene expression levels of ligands and receptors previously linked to the SOX10/MITF axis." (PMID 36251678, 2023). "While much of the existing data on the role of SOX10 in neoplasms primarily focuses on melanoma, this gene is also implicated in other neural and neuroectodermal tumors." (PMID 38132479, 2023). "Increased transcriptional levels of SOX10 are suggested to desensitize BRAF‐mutant melanoma to MAPK inhibition, however, loss of SOX10 has also been shown to drive acquired resistance." (PMID 36251678, 2023). "In light of the diverse yet persistent role of SOX10 in melanoma cells, its potential as a diagnostic histopathological marker has been explored." (PMID 38132479, 2023). "Resistance to vemurafenib can be induced by the loss of SOX10, a common proliferative marker in melanoma." (PMID 38201278, 2023). "In melanoma, regulated by fat mass and obesity-associated protein, enrichment of SOX10 decreases the effect on anti-PD-1 blockade immunotherapy." (PMID 36524115, 2022). "We show that the expression of SOX10 can direct melanoma cells towards a proliferative state and that its loss leads to invasive characteristics." (PMID 35296667, 2022). "Immunohistochemical staining shows a positive reaction to melanoma‐associated markers such as SOX10, HMB‐45, HMB‐50, Melan A, MITF, and NKI‐C3 and myogenic markers like SMA, but not to epithelial markers such as cytokeratin." (PMID 36056704, 2022). "In the other 12 melanomas, SOX10-expressing and SOX10-deficient cells co-existed within the same tumor lesion." (PMID 35296667, 2022). "Previous studies revealed that during melanoma progression, melanoma cells develop stem-cell like properties associated with the expression of SOX10, EZH2 transcription factors, EMT phenotypic switch regulators TWIST1/ZEB1, and the surface receptor CD172." (PMID 35269844, 2022).
melanoma (continued). "Since SOX10 was associated with OS of late-stage melanoma patients in the TCGA dataset, it is plausible that the SOX10 expression level is a prognostic marker in melanoma, and is not linked to any specific treatment response." (PMID 35058553, 2022). "EGFR, along with SOX9, are upregulated in melanoma cells with undifferentiated phenotypes, and their expressions are induced by the loss of SOX10." (PMID 35406721, 2022). "Together, our findings provide a strategy to target SOX10-deficient subpopulations and reduce drug-tolerant populations in melanoma." (PMID 35296667, 2022). "Our study shows that SOX10-deficient melanoma cells are slow-cycling, which is an effect associated with reduced expression of MITF and cyclin D3 as well as enhanced p21Cip1." (PMID 35296667, 2022). "This is reminiscent of melanoma cells displaying reduced SOX10 levels, which is associated with increased expression of SOX9, another factor involved in NC development, and increased invasiveness." (PMID 34417458, 2021). "Disrupted in Renal Carcinoma 3 (DIRC3) lncRNA is transcriptionally repressed by microphthalmia-associated transcription factor (MITF)- SRY-box transcription factor 10 (SOX10) pathway in melanoma." (PMID 34638331, 2021). "We have previously identified the transcription factor Sox10 as a crucial player in melanoma, yet the underlying molecular mechanisms mediating Sox10-dependent tumorigenesis remain largely uncharacterized." (PMID 32238882, 2020). "Here we have identified a new set of 245 candidate melanoma-associated lncRNAs that are targeted by the MITF and SOX10 melanoma transcription factors." (PMID 31881017, 2019). "On the other hand, previous studies showed that either overexpression of SOX9 alone or upregulation of SOX9 expression in SOX10 KD caused cell cycle arrest through an increase in cyclin-dependent kinase inhibitor p21 protein expression in melanoma cell lines." (PMID 30642390, 2019). "Here we show that lncRNAs are also important components of MITF-SOX10-driven transcriptional programmes and identify 245 candidate melanoma-associated lncRNAs whose loci are co-bound by MITF and SOX10." (PMID 31881017, 2019). "The presence of super-enhancers close to the sox10 gene was associated with elevated sox10 expression both human melanoma cells and in a zebrafish melanoma model." (PMID 29049289, 2017). "Here, we show that this anti-tumorigenic effect functionally involves SOX9, a factor related to SOX10 and upregulated in melanoma cells upon loss of SOX10." (PMID 25629959, 2015). "Second, when inspecting Affymetrix Exon Array expression data from ENCODE/Duke, we found SOX10 to be specifically upregulated in melanoma cell lines." (PMID 26013289, 2015). "SOX10 is known to act as a specifier of neural crest derivatives and directly regulates melanoma associated genes like ERBB3, EDNRB and MITF." (PMID 24799129, 2014). "SOX9 and SOX10, overexpressed in melanomas, are implicated in the regulation of genes involved in melanogenesis such as MITF and tyrosinase." (PMID 24086527, 2013). "Expression of TAM67 caused increased expression of SOX10 in both human melanoma (∼2 folds) and melanocytes (∼3 folds), indicating some relief of JunB inhibition." (PMID 21203491, 2010). "Similarly, the transcription factor (Sex Determining Region Y)-box 10 (SOX10) modulates melanoma cell susceptibility to T cell-mediated killing." (PMID 41235238, 2025). "Together, our findings support a model in which SOX10 loss promotes a shift toward a drug-tolerant melanoma cell state characterized by increased reliance on TEAD-driven transcription and sensitivity to TEAD inhibition, indicating a context-dependent vulnerability." (PMID 41193428, 2025). "SOX10-deficient melanoma cells show invasive features and tolerance to BRAFi and/or MEKi18." (PMID 41193428, 2025).